ERCC1 (ERCC excision repair 1, endonuclease non-catalytic subunit)
Diseases named in the same sentence as ERCC1 in open-access papers (continued):
Sharing a sentence is not in itself a finding about the gene and the disease.
gastric cancer (continued). "And the ERCC2 rs1799793 polymorphism, together with ERCC1 rs11615 polymorphism, may play roles in the response to chemotherapy and overall survival for patients with gastric cancer." (PMID 28388903, 2017). "ERCC1 rs2298881C and rs11615A variant genotypes were associated with increased gastric cancer risk (adjusted OR = 1.33, 95% CI = 1.05–1.67 for rs2298881 AC/CC and adjusted OR = 1.23, 95% CI = 1.05–1.46 for rs11615 AG/AA, compared with their common genotype AA and GG, respectively)." (PMID 23166636, 2012). "We further evaluated the association between variant genotypes of three selected SNPs of ERCC1 and gastric cancer risk stratified by subgroups of age, sex, smoking and drinking status, tumor site and clinical stage, assuming a dominant genetic model based on the results from univariate analysis." (PMID 23166636, 2012). "The expression of ERCC1 mRNA was suggested as a predictive and prognostic marker in resectable gastric cancer patients receiving chemotherapy." (PMID 39516666, 2024). "Recurrent gastric cancer patients with ERCC1 rs3212964, ERCC1 rs2298881, or GSTP1 rs1695 SNPs had higher ERCC1 expression and had a worse OS." (PMID 39516666, 2024). "In conclusion, we believe that this is the first study to evaluate the prognostic and predictive value of ERCC1 gene alteration, ERCC1 mRNA expression, and GSTP1 polymorphism in patients with unresectable or recurrent gastric cancer." (PMID 39516666, 2024). "S-1 was effective in ERCC1-high patients with resectable stage II or III gastric cancer after surgery in the adjuvant setting." (PMID 39516666, 2024). "When the results are evaluated, it is reported that compound 3 has a good prognosis among gastric cancer in correlation with the studies employing high ERCC1 gene expressions." (PMID 37895364, 2023). "This study proposed that activated ERK1/2 and p38 kinases play a role in developing drug resistance via upregulating ERCC1 expression in gastric cancer." (PMID 37248432, 2023). "The low expression of compound 2 in ERCC1 in AGS gastric cancer cells shows that it significantly reduces cellular viability, which correlates with a decreased DNA repair capacity." (PMID 37895364, 2023). "A study showed a decrease in chemoresistance, and an increase in the survival time was observed in patients with HER2 overexpressing gastric cancer and low ERCC1 expression compared to the patients with high ERCC1 expression." (PMID 36338712, 2022). "MiR-138-5p regulated the cisplatin resistance by modulating the expression of the DNA repair proteins ERCC4 and ERCC1 in gastric cancer cells." (PMID 34993023, 2021). "ERCC1 SNPs have shown to have prognostic and/or predictive value in the advanced (metastatic) gastric cancer setting 17, 19, 35, 42-44." (PMID 31602266, 2019). "The genotypes of ERCC1 rs11615 and ERCC2 rs1799793 were revealed to affect the response to chemotherapy, and were associated with the OS in gastric cancer patients." (PMID 26622786, 2015). "Several recent reports demonstrated that high-level expression of ERCC1 was correlated with platinum resistance and poor recurrence-free survival and OS in gastric cancer." (PMID 24053422, 2013). "The correlation between ERCC1 mRNA expression levels and the chemosensitivity of platinum agents in 7 gastric cancer cell lines was subsequently determined." (PMID 23426424, 2013). "As a supplement to the previous studies, the current study further demonstrated that higher APTX, BRCA1 and ERCC1 mRNA expression levels suggested lower likelihood of response to irinotecan-based chemotherapy in gastric cancer." (PMID 23517622, 2013). "Univariate and multivariate analyses of associations between ERCC1 genotype, ERCC2 genotypes, combined ERCC1 and ERCC2 variants and overall survival in gastric cancer patients." (PMID 24023723, 2013). "ERCC1 mRNA levels in gastric cancer cell lines and gastric cancer tissues were significantly higher than those in adjacent normal tissues (P<0.05)." (PMID 23426424, 2013).
gastric cancer (continued). "Gastric cancer patients with low levels of ERCC1 expression demonstrate a benefit from oxaliplatin-based adjuvant chemotherapy." (PMID 23426424, 2013). "Univariate and multivariate analyses of associations between ERCC1 and ERCC2 haplotypes and overall survival in gastric cancer patients." (PMID 24023723, 2013). "In the present study, we assessed associations of ERCC1 (rs3213986) and ERCC2 (rs13181, and rs1799793) SNPs with survival in gastric cancer patients." (PMID 24023723, 2013). "Gene expression levels of APTX, BRCA1 and ERCC1 were significantly lower in irinotecan-sensitive gastric cancer samples than those irinotecan-resistant samples (P < 0.001 for all genes), while ISG15 (P = 0.047) and Topo1 (P = 0.002) were significantly higher." (PMID 23517622, 2013). "Additional prospective, randomized controlled trials are needed to identify the true significance of TUBB3 and ERCC1 in the prognosis of gastric cancer." (PMID 24053422, 2013). "The ERCC1 expression levels were first examined in 7 gastric cancer cell lines, tumor tissues and adjacent normal tissues by qRT-PCR." (PMID 23426424, 2013). "ERCC1 is currently under investigation in gastric cancer, but the influence of ERCC1 expression remains controversial." (PMID 24053422, 2013). "Stratification analysis for associations between ERCC1 and ERCC2 SNPs and overall survival in gastric cancer patients." (PMID 24023723, 2013). "Logistic regression analysis of associations between selected ERCC1 and XPF/ERCC4 SNPs and gastric cancer risk in an Eastern Chinese population." (PMID 23166636, 2012). "A recent study used immunohistochemistry to examine ERCC1 expression in the primary tumours of 64 patients with advanced gastric cancer treated with 5-FU/oxaliplatin chemotherapy." (PMID 20461087, 2010). "In patients with curatively resected gastric cancer, it was shown that increased ERCC1 expression was correlated with improved outcome." (PMID 19259093, 2009). "Distal gastric cancer was present in 62.3% of patients with low ERCC1 levels and proximal gastric cancer was present in 53.3% of patients with high ERCC1 levels (P=0.02)." (PMID 18362936, 2008). "We observed the significant interaction of BRCA1 and ERCC1 mRNA expression levels on sensitivity to cisplatin in total and gastric cancer patients." (PMID 18402708, 2008). "ERCC1 and TS mRNA levels were examined in 38 of the 65 gastric cancer patients, for whom sufficient cDNA was available." (PMID 18362936, 2008). "A study assessing ERCC1 and TS by immunostaining in 64 advanced gastric cancer patients treated with FOLFOX also showed significant differences according to ERCC1 expression." (PMID 18362936, 2008). "Low levels of TS have been observed in oxaliplatin-resistant gastric cancer cell lines, providing a plausible potential explanation of why a meaningful number of patients with low ERCC1 and high TS levels had the longest survival in the present study." (PMID 18362936, 2008). "Our previous ancillary investigation of another randomized controlled trial, JCOG9912, showed that low ERCC1 expression was a significant independent favorable prognostic factor in patients with advanced gastric cancer who were also receiving first-line chemotherapy." (PMID 39516666, 2024). "ERCC2 rs50871 G/T, ERCC6 rs1917799 G/T and DDB2 rs3781619 A/G polymorphisms were significantly associated with shorter OS, while ERCC1 rs3212961 A/C, ERCC5 rs2094258 A/G and DDB2 rs830083 C/G could predict favorable OS of gastric cancer patients." (PMID 35955506, 2022). "Conflicting clinical trial reports exist regarding the role of ERCC1 expression in predicting cisplatin treatment on gastric cancer: some claimed that patients benefit more from low ERCC1 expression, some stated the opposite, while still others found no connection at all." (PMID 31331301, 2019).
gastric cancer (continued). "ERCC1 plays a key role in the DNA repair pathway, and has been demonstrated that lung and gastric cancer patients with lower mRNA expression levels of ERCC1 could benefit from platinum-based chemotherapy." (PMID 23762305, 2013). "We examined gene expression of APTX, BRCA1, ERCC1, ISG15, Topo1 and methylation of SULF2 in formalin-fixed paraffin-embedded gastric cancer tissues from 175 patients and evaluated the association between gene expression levels or methylation status and in vitro sensitivity to irinotecan." (PMID 23517622, 2013). "We have also reported that immunohistochemical staining for ERCC1 may be useful in prediction of the clinical outcome in advanced gastric cancer patients treated with modified FOLFOX4." (PMID 23876227, 2013). "However, a limited number of gastric cancer studies have focused on the effect of ERCC1 expression on the outcome of FOLFOX adjuvant chemotherapy." (PMID 23426424, 2013). "We reported that immunohistochemical staining for Excision Repair Complementation 1 (ERCC1) may be useful in prediction of the clinical outcome in advanced gastric cancer patients treated with modified FOLFOX4." (PMID 23374220, 2013). "The present study was designed to evaluate the effects of ERCC1 expression on the chemosensitivity of platinum agents in gastric cancer cell lines, and on survival in gastric cancer patients treated with surgery followed by oxaliplatin-based adjuvant chemotherapy." (PMID 23426424, 2013). "In conclusion, the present results support the theories that ERCC1 may participate in platinum resistance in gastric cancer cells, and that high ERCC1 expression may be a poor predictor of efficient oxaliplatin-based adjuvant chemotherapy." (PMID 23426424, 2013). "In our study, we found the ERCC1 expression levels were inversely associated with the chemosensitivity of platinum agents in 7 gastric cancer cell lines, and the inhibition of ERCC1 expression by siRNA sensitized the effects of cisplatin and oxaliplatin in the relatively resistant MKN45 cells." (PMID 23426424, 2013). "Since the time of writing the present report, another study in paraffin-embedded tumour tissue has confirmed the role of ERCC1 mRNA expression in a heterogeneous cohort of gastric cancer patients – 69 treated with S-1, 23 with 5-FU and 43 with cisplatin plus either irinotecan or S-1." (PMID 18362936, 2008). "In addition, BRCA1 mRNA expression was negatively correlated with cisplatin sensitivity in peritoneal effusions of gastric cancer patients, while ERCC1 was correlated with cisplatin sensitivity only in specimens of untreated gastric patients." (PMID 18402708, 2008). "Excision repair cross-complementing 1 (ERCC1) and thymidylate synthase (TS) mRNA expression levels were assessed in advanced gastric cancer tumour samples using real-time quantitative PCR in 76 patients treated with a modified FOLFOX (biweekly oxaliplatin plus 5-FU and folinic acid) regimen." (PMID 18362936, 2008). "In vitro and clinical data show that ERCC1 expression is negatively associated with response to cisplatin or oxaliplatin chemotherapy in gastric and colon cancer and high-tumour tissue levels of ERCC1 mRNA confers cisplatin resistance in ovarian and gastric cancer patients." (PMID 22275966, 2008). "There is a report suggesting that high levels of ERCC1 expression in gastric cancer may be associated with poor survival and a lack of response to cisplatin; however, its role remains controversial." (PMID 24053422, 2013). "In this first QPCR analysis of ERCC1 and TS mRNA expression in formalin-fixed paraffin-embedded tumour tissue in advanced gastric cancer, we have found that ERCC1 – but not TS – mRNA expression is associated with survival in patients receiving a modified FOLFOX regimen." (PMID 18362936, 2008). "First, we were unable to explore the exact mechanism by which ERCC1 and ERCC2 SNPs influence gastric cancer survival." (PMID 24023723, 2013).
gastric cancer (continued). "We genotyped by the TaqMan assay three common, potentially functional ERCC1 (rs3212986) and ERCC2 SNPs (rs13181 and rs1799793) in 360 gastric cancer patients." (PMID 24023723, 2013). "We analyzed the significance of TUBB3 expression, along with that of excision repair cross-complementation group 1 (ERCC1) in recurrent and metastatic gastric cancer patients receiving taxane-based first-line palliative chemotherapy." (PMID 24053422, 2013). "Our results demonstrate that ERCC1 and BRCA1 mRNA expression levels are correlated with in vitro chemosensitivity to cisplatin and/or docetaxel in malignant effusions of NSCLC and gastric cancer patients." (PMID 18402708, 2008). "To further clarify the prognostic value of TS and ERCC1 mRNA expression, we examined by QPCR 76 formalin-fixed paraffin-embedded tumour samples from FOLFOX-treated advanced gastric cancer patients and correlated the results with survival." (PMID 18362936, 2008). "We observed a clear correlation between ERCC1 and BRCA1 mRNA expression level and chemosensitivity to cisplatin, one of the most widely used agent in both NSCLC and gastric cancer." (PMID 18402708, 2008). "This study was designed to evaluate the effect of excision repair cross complementing group 1 (ERCC1) rs11615 codon 118C/T gene polymorphisms on treatment outcomes in Iranian patients receiving oxaliplatin-based regimens for colorectal (CRC) and gastric cancers (GC)." (PMID 32184881, 2019). "In conclusion, these results suggest that ERCC1 rs11615 and ERCC2 rs1799793 in the DNA repair pathways may be used as predictive factors of the clinical outcome in gastric cancer patients." (PMID 26622786, 2015). "In conclusion, the results of the present study suggest that the ERCC1 rs11615 and ERCC2 rs1799793 SNPs in DNA repair pathways may be utilized as predictive factors of the clinical outcome in gastric cancer patients." (PMID 26622786, 2015). "In summary, we found that ERCC1 and ERCC2 functional SNPs may independently (rs1799793) and jointly (rs1799793, rs13181 and rs3212986) affect the OS in North American gastric cancer patients." (PMID 24023723, 2013). "In the present study, we investigated whether functional ERCC1 rs3213986 G>T and ERCC2 rs13181 T>G and rs1799793 G>A SNPs have any individual or joint effects on clinical outcomes of gastric cancer patients in a North American patient population." (PMID 24023723, 2013). "However, few studies have simultaneously investigated the roles of ERCC1 and ERCC2 SNPs in clinical outcomes in gastric cancer patients." (PMID 24023723, 2013). "Moreover, ERCC1 had no clinical effect on progression-free survival or overall survival in gastric cancer patients." (PMID 29632637, 2018). "Another study has previously investigated the association between three functional SNPs in DNA repair pathways and the clinical outcome of 940 cases of gastric cancer in a Chinese population, and reported that ERCC1 rs11615 did not affect the OS of gastric cancer patients." (PMID 26622786, 2015). "The role of ERCC1 in advanced gastric cancer has not been extensively evaluated." (PMID 24053422, 2013). "ERCC1 and ERCC2 functional SNPs may jointly affect OS in Caucasian gastric cancer patients." (PMID 24023723, 2013). "In summary, this large hospital-based case-control study provided statistical evidence that ERCC1 rs2298881 and rs11615 SNPs, but not ERCC4 SNPs, were associated with gastric cancer risk in an Eastern Chinese population, particularly for never-drinkers, patients with NGCA and early clinical stages." (PMID 23166636, 2012). "Therefore, the present study was to investigate whether the genes ERCC1, BRCA1, TYMS, RRM1, TUBB3, STMN1 and TOP2A are underlying biomarkers for patients with gastric cancer, which, to our knowledge, has not been performed." (PMID 28056823, 2017).
gastric cancer (continued). "Except for excision repair cross-complementing 1 (ERCC1), mRNA expression of the remaining ERCC genes has not been investigated in the prognosis of gastric cancer (GC)." (PMID 30417012, 2018).
breast carcinoma (46 papers, 2005 to 2025). "They noted that in locally advanced breast cancers, low ERCC1 expression was associated with high pCR and low distant relapse rates." (PMID 40008380, 2025). "In breast cancer, the landscape of NER-related genetic mutations varies by races; increased risks of developing breast cancer in women are found to be correlated with different ERCC1, XPC, or XPD polymorphisms in postmenopausal Chinese and American women." (PMID 39334297, 2024). "Previous studies have shown that the ERCC1 rs11615 variant is associated with breast cancer and pancreatic cancer risk." (PMID 35637613, 2023). "Protein expression of PARP1, X-ray cross complementing protein 4/1 (XRCC4, XRCC1), and ERCC1 were risk factors for postoperative metastasis of breast cancer." (PMID 36612206, 2022). "The decrease in expression of ERCC1 and genes associated with DNA damage repair arrest the cell cycle at the G1-S phase in breast cancers, thereby altering the regulation of the cell cycle by ER." (PMID 36338712, 2022). "This study aimed to explore the roles of ERCC1/XPF gene polymorphisms in the occurrence of breast cancer in the Uygur and Han ethnic groups in Xinjiang, China." (PMID 33067872, 2020). "Our results showed that ERCC1/XPF gene polymorphisms predispose Uygur individuals to breast cancer; this finding should be verified by further large‐scale analyses." (PMID 33067872, 2020). "In summary, our study showed that ERCC1/XPF gene polymorphisms in the Uygur group predispose individuals to breast cancer." (PMID 33067872, 2020). "The combined diagnosis of the PARR1, XRCC4 and ERCC1 have greater predictive value for the risk of metastasis of breast cancer (Se = 94.17%, Sp = 75.73%; OR 11.739, 95% CI 2.858 ~ 40.220, P < 0.05)." (PMID 33184404, 2020). "To summarize, these findings indicate that ERCC1 rs11615 (C>T) was associated with breast cancer risk." (PMID 30096175, 2018). "In our current study, two ERCC1 polymorphisms (rs11615 C>T and rs3212986 T>G) were studied and compared between healthy controls and breast cancer patients." (PMID 30096175, 2018). "A Chi-square test was performed to investigate the association of ERCC1 rs11615 genotypes with breast cancer risk." (PMID 30096175, 2018). "Our findings firstly show that the T allele of ERCC1 rs11615 can serve as a predictive biomarker for breast cancer and TNBC." (PMID 30096175, 2018). "The rs11615 and rs3212986 of ERCC1 were investigated and evaluated for their associations with susceptibility to breast cancer, especially TNBC, in Taiwan." (PMID 30096175, 2018). "Our results suggest that the ERCC1 rs11615 polymorphism is associated with breast cancer susceptibility, and in particular, this increased risk of breast cancer existence in Asian population." (PMID 29752341, 2018). "We found that the ERCC1 rs11615 polymorphism was significantly associated with breast cancer risk under all genetic models." (PMID 29752341, 2018). "Association of Excision Repair Cross-complementing Group 1 (ERCC1) rs11615 genotypes with breast cancer risk stratified by clinicopathologic characteristics compared with non-cancer healthy controls." (PMID 30096175, 2018). "Here, we looked for powerful evidence that either supports or refutes the validity of associations between the ERCC1 rs11615 polymorphism and breast cancer risk." (PMID 29752341, 2018). "In the current investigation, we aimed at discovering the contributions of ERCC1 rs11615 and rs3212986 genotypes to breast cancer susceptibility in a large population of Taiwanese females, including 1,232 breast cancer cases and 1,232 healthy controls." (PMID 30096175, 2018). "As a consequence, it is still too early to tell the role that the ERCC1 rs11615 polymorphism plays in breast cancer risk variation in different ethnic backgrounds." (PMID 29752341, 2018).